ARID1B (AT-rich interaction domain 1B)
Diseases named in the same sentence as ARID1B in open-access papers (continued):
Sharing a sentence is not in itself a finding about the gene and the disease.
cancer (continued). "More importantly 9 new cancer genes were identified; seven of them (ARID1B, CASP8, MAP3K1, MAP3K13, NCOR1, SMARCD1, CDKN1B) carried truncating mutations and were characterized by biallelic inactivation, suggesting that they were potentially recessive cancer susceptibility genes." (PMID 26561834, 2015). "The depletion of ARID1A and ARID1B leads to a reduction in the accessibility of AP‐1 binding sites, a decrease in the distance between nucleosomes, and affects the binding of AP‐1 transcription factors, thereby influencing the expression of multiple cancer‐related genes, including MET." (PMID 39779467, 2025). "Furthermore, we found that mutations of KRAS and ARID1B were also mutually exclusive in right-site cancer, but not in other sites." (PMID 36439454, 2022). "The pausing defect could be rescued by upregulation of ARID1B, suggesting that both ARID1A and ARID1B control transcription via RNApol2 pausing and that dysregulated pausing likely mediates effects of ARID1A loss in cancers and possibly also neurodevelopmental disorders." (PMID 35615272, 2022). "Our results that five epidriver candidates (SRCAP, EP400, ARID1B, MBD5, and KMT2A) among the top 15 ERGs enriched in EMT fraction were found among the most mutated ERGs in clinical samples across cancer types support the driver role of EMT-specific ERG tumorigenesis." (PMID 32963031, 2020). "Inhibition of importin subunit KPNB1 by IPZ hindered ARID1B nuclear translocation, potentially disrupting SWI/SNF function in cancer cells." (PMID 40671262, 2025). "SWI/SNF mutations occur at a high frequency in TC, primarily involving the inactivation of SWI/SNF subunits ARID1A, ARID1B, ARID2, and PMRM1, which were found in several aggressive cancer types, including ATC." (PMID 40203790, 2025). "Hence, ARID1A-mutated tumours may depend on ARID1B for proliferation, suggesting a synthetic lethality combination between ARID1A and ARID1B and thus providing an opportunity for personalised targeting of cancer growth." (PMID 41278204, 2025). "ARID1B, a paralogue of ARID1A, is among the top genes first identified that are preferentially required for the survival of ARID1A-mutant cancer cells." (PMID 36980292, 2023). "Genetic alterations in ARID1A (12%), ARID1B (5%), ARID2 (6%) and ARID5B (2.6%) were identified in multiple cancer types." (PMID 35239432, 2022). "The mutational rates and variation types of six SWI/SNF complex genes (ARID1A, ARID1B, ARID2, SMARCA4, SMARCB1, and PBRM1) were analyzed retrospectively by integrating next-generation sequencing data of 4591 cases covering 18 cancer types." (PMID 36371186, 2022). "It was reported that the ARID1A homolog, which is ARID1B, is required for the survival of ARID1A-mutant cancer cell lines." (PMID 32245111, 2020). "Similar to the ARID1A/ARID1B functional dependency, SMARCA4 mutant cancer cells showed sensitivity to SMARCA2 depletion." (PMID 31769422, 2019). "Among these proteins, we have identified many differentially abundant proteins identified as having a role in cancer (IFIT1, FASTKD2, PIP4K2B, ARID1B, SLC25A33: overexpressed in TR; CALD1, CPA3, B3GALT5, CD177, RIPK1: overexpressed in NR)." (PMID 29681787, 2018). "This analytical approach has led, for example, to the discovery of ARID1B and SMARCA2 as specific vulnerabilities for ARID1A and SMARCA4-mutant cancers, respectively." (PMID 27296290, 2016).
cancer (continued). "Our study reveals a biochemical function of ARID1A/ARID1B in BAF-mediated chromatin remodeling, suggesting a model in which dysregulation of histone octamer transfer activity of BAF complexes may lead to cancer formation." (PMID 41017120, 2025). "To illustrate the context-dependency of synthetic lethality, we further analyzed the cell type dependencies on ARID1B in cancers with or without ARID1A-deficinecy across 32 cancer types." (PMID 36980292, 2023). "BRD2 inhibitors reduce ARID1B and other SWI/SNF member expression in ARID1A mutant cancers." (PMID 36430148, 2022). "We identified HBV integrations with high integration allele fractions in tumors in seven non-recurrent cancer-related genes, including GAS7, NSP, RSPO2, NRG1, PRDM16, ARID1B, and AFF1." (PMID 33557409, 2021). "Additionally, our research is the first to investigate the role of ARID1B, which is another ARID1 subunit similar to ARID1A, in changing the phenotype of cancer." (PMID 32791957, 2020). "ARID1B, a structurally related but mutually exclusive homolog of ARID1A in the SWI/SNF chromatin-remodeling complex, is a potential synthetic lethal vulnerability in ARID1A-mutant human cancers." (PMID 32967217, 2020). "ARID1B, an isoform that is mutually exclusive with ARID1A in the SWI/SNF complexes and that is involved in regulating transcription and multiple downstream cellular processes, has been recently identified to be the primary mutant gene in various cancers." (PMID 32162380, 2020). "We have identified many differentially abundant proteins already identified as having a role in cancer, such as the earlier discussed proteins IFIT1, FASTKD2, PIP4K2B, ARID1B and SLC25A33 (more abundant in TR) or CALD1, CPA3, B3GALT5, CD177 and RIPK1 (more abundant in NR)." (PMID 29681787, 2018). "The reason for the selectivity for ARID1A mutations in cancer is not understood, and the functional basis for the synthetic lethal relationship between ARID1A and ARID1B has not yet been determined." (PMID 28967863, 2017). "Our study reveals a biochemical function of ARID1A/ARID1B in BAF-mediated chromatin remodeling, suggesting a model in which dysregulation of histone octamer transfer activity of BAF complexes may be relevant to cancer formation." (PMID 41017120, 2025). "An in vitro study showed that ARID1B is a specific determinant of the SWI/SNF complex, has a broad role in promoting proliferation, and also plays a significant role in inhibiting cell cycle activity, making it an attractive therapeutic target for cancer treatment." (PMID 38365747, 2024). "The reason for this could be that cancer cells lacking ARID1A and ARID1B expression are deficient in DNA repair and potentially vulnerable to DNA damage." (PMID 33467469, 2021). "Another study demonstrated that the chromatin-remodeling factor ARID1B, forming the BAF complex together with ARID1A, represses the Wnt/ß-Catenin signaling pathway indicating this might contribute to cancer through deregulation of developmental and oncogenic pathways." (PMID 29451900, 2018). "While conventional cancer driver genes of sporadic PC were not involved in our case, deletions were identified in the tumor suppressor genes CDKN2A, LATS1, ARID1A, and ARID1B." (PMID 40362680, 2025). "In this case, cancer cells lacking SMARCA4 or ARID1A, two core components of the SWI/SNF complex, become dependent on the corresponding paralogs, SMARCA2 and ARID1B, respectively." (PMID 28430577, 2017).
cancer (continued). "Wild-type ARID1A and ARID1B are located at the promoter of CD274 in OCCC cells (shown in the human OVCA429 and RMG1 cell lines, as well as mouse ovarian ID8-Defb29/Vegf cancer cells), although ARID1B was not able to influence the levels of CD274 in ARID1A knockout (KO) cells." (PMID 39272926, 2024).
tumor (83 papers, 2013 to 2026). "In animal experiments, the tumor formation speed of ARID1B gene deficient cells was significantly accelerated." (PMID 40210476, 2025). "The EPIC analysis and MCPcounter analysis revealed a positive correlation between ARID1B and tumor-associated fibroblasts." (PMID 38577613, 2024). "Multivariate data analysis further suggests that ARID1B expression level is an independent predictive factor for tumor size, tumor grade, and nuclear polymorphism." (PMID 38365747, 2024). "Inversely, CHOL showed enrichment for increased NRF2 signaling with three of four subunit mutations, with the exception of ARID1B, suggesting a tumor-specific response as well." (PMID 38358974, 2024). "Considering the close relationship between ARID1A and ARID1B, it would be compelling to investigate their tumor site-specific associations with KRAS pathway in future research." (PMID 36439454, 2022). "ARID1B is a preferred gene for the survival of ARID1A-mutant tumor cell lines, while loss of ARID1B in the background of ARID1A mutation destabilizes the SWI/SNF complex and impairs cell proliferation." (PMID 34671561, 2021). "Although inactivating mutations were only seen in ARID1A and ARID1B genes, IHC only confirmed loss of ARID1B in VOA1066 primary tumor and cell line." (PMID 33052929, 2020). "This patient had six verified tumor mutations (ARID1B, ATM, CDK8, FANCA, and two RASA1 mutations), all of which were detected in the preoperative plasma sample." (PMID 30554450, 2019). "Whereas three high-risk patients with relapsed tumors with neither MYCN amplification nor ARID1B mutations were rescued with salvage treatment after relapse, two relapsed patients with ARID1B mutations died of tumor progression." (PMID 28521285, 2017). "Our results demonstrate a role for ARID1A and ARID1B in maintaining chromatin accessibility and define nucleosome remodeling as a critical function underlying the tumor suppressor role of ARID1A and the synthetic lethal relationship of ARID1A and ARID1B." (PMID 28967863, 2017). "Such a mechanism could underlie ARID1B‐driven oncogenesis, wherein elevated ARID1B suppresses tumor‐suppressive ARID1A, thereby altering the ARID1A‐dependent transcriptome to promote tumorigenesis." (PMID 40671262, 2025). "This suggests that ARID1B activity may be essential for tumor growth in the context of ARID1A mutation or downregulation." (PMID 40671262, 2025). "While this has yet to result in a new therapy for ARID1A-mutated tumours, the identification of a drug(s) that targets and abolishes ARID1B function in ARID1A-mutated tumours could represent a new therapeutic strategy for OCCC." (PMID 39272926, 2024). "In a study of 55 OCCC, the ARID1A paralogue ARID1B was reported to be mutated in 18% of tumours." (PMID 39272926, 2024). "Furthermore, our study revealed an additional mechanism by which ARID1B deficiency can influence the tumor microenvironment and enhance the response to immunotherapy." (PMID 38577613, 2024). "We analyzed the differences in DNA methylation levels in the TCGA COAD cohort and determined the association between ARID1B methylation and clinicopathological variables, including age, gender, tumor stage, lymph metastasis, distant metastasis, and clinical stage." (PMID 36313455, 2022). "All tumor samples had complete loss of ARID1B protein expression, but retained ARID1A expression." (PMID 33052929, 2020). "Mechanistically, miR-32-5p activates the cyclic GMP-AMP synthase (cGAS)-stimulator of interferon genes (STING) signaling pathway through ARID1B down-regulation, ultimately remodeling the tumor immune microenvironment." (PMID 41608526, 2026).
tumor (continued). "One tumor had only a point mutation in NTRK1, while the remaining tumor showed 11 heterozygous deletions, including in ROS1, BCLAF1, and ARID1B, which were frequently altered in the entire cohort." (PMID 40227833, 2025). "Our search for such targets, using big data analyses and pathological validation based on patient specimens, has drawn our attention to ARID1B as an important factor in mediating tumor growth and pathogenesis." (PMID 40671262, 2025). "Here, we demonstrated that depletion of ARID1B or inhibition of its nuclear translocation reduces tumor growth and enhances the therapeutic efficacy." (PMID 40671262, 2025). "Pharmacological inhibition of KPNB1 blocked ARID1B translocation from the cytosol to the nucleus, impeding tumor growth." (PMID 40671262, 2025). "This trend suggests a contributory role of ARID1B in tumor aggressiveness, possibly via chromatin remodeling or transcriptional regulation." (PMID 40806597, 2025). "Tumor growth in these mutant groups remained significantly suppressed and comparable to that of the ARID1B KO control group." (PMID 40671262, 2025). "Disrupting ARID1B nuclear import suppresses tumor progression and enhances sensitivity to PARP inhibitors." (PMID 40671262, 2025). "Using RT‒PCR and the available tumor samples, we validated ARID1B-ZDHHC14 and CSNK1D-CCDC57, suggesting their potential biological relevance and warranting further investigation." (PMID 40925909, 2025). "These transcriptional changes are consistent with a suppression of tumor growth upon ARID1B downregulation." (PMID 40671262, 2025). "In TNBC mouse models, ARID1B knockout (KO) significantly reduces tumor growth and enhances PARP inhibitor efficacy." (PMID 40671262, 2025). "The whole-exome sequencing revealed a variety of common oncogenic mutations in the original tumor and HMucBOT-2, including KRAS, ARID1A, ARID1B, and NF1, while CDKN2A remained wild-type." (PMID 40427213, 2025). "A shift from ARID1A‐ to ARID1B‐bound BAF complexes can result in a switch from tumor‐suppression to oncogenesis action in SWI/SNF chromatin remodelers." (PMID 40671262, 2025). "The ARID1B (BAF250b) subunit is a typical nuclear tumor suppressor; however, ARID1B localized in the cytoplasm can interact with c-RAF (RAF1) and PPP1CA, thereby stimulating RAF-ERK signaling and β-catenin transcriptional activity." (PMID 39609317, 2024). "Loss of ARID1A cannot be compensated by increasing ARID1B expression, and in most tumor samples, the expression of ARID1B is also lower than that of ARID1A, suggesting that ARID1B is necessary for promoting tumor development in ARID1A mutations." (PMID 38365747, 2024). "Tumours in which both ARID1A and ARID1B are mutated are reported to retain a wild-type allele of ARID1B, providing evidence that a certain level of wild-type ARID1B is essential to avoid synthetic lethality in ARID1A-mutant tumours." (PMID 39272926, 2024). "Even epigenetic changes are involved in this tumor biology, such as key mutations in chromatin remodeling (MERC1, SMARCA2, ARID1A, ARID1B, SMARCA4) and an imbalance in miRNAs (miR-155, miR-320a, miR-99a, miR-205) that regulate gene expression." (PMID 37476370, 2023). "First of all, novel drivers identified through integrative analysis, especially the chromatin remodelling genes (e.g. ARID1B), are often late-occurring tumor suppressors." (PMID 35832070, 2022). "Differential analysis of total of 82 RNA-Seq data using TNMplot database showed that ARID1B had a lower mRNA level in tumor COAD tissues (41 patient) compared to normal tissues (41 patient)." (PMID 36313455, 2022). "The correlation analysis was also carried out between ARID1B and the tumour immune infiltration level in COAD." (PMID 36313455, 2022). "This tumour carried nonsense somatic mutations in ARID1A with putative bi-allelic inactivation (2 frameshifts 556 and 1005/p2285) and a nonsense mutation in ARID1B (one stop gained R1944X)." (PMID 31844183, 2020).
tumor (continued). "One tumour showed a disrupting mutation and LOH of ARID1B and two tumours each harboured two truncal mutations in ARID1A, which are all members of the SWI/SNF-chromatin-modifying complex." (PMID 31949146, 2020). "In the one SMARCA4 wild-type tumor (IGR-03) which showed concomitant ARID1A and ARID1B mutations, SMARCA2 expression was higher at the mRNA level (real-time RT-PCR) than in SMARCA4 mutated samples, and interpreted as ambiguous/low at the protein level (IHC)." (PMID 32575483, 2020). "Mutations in the chromatin remodelling genes ARID1B and ARID1A were found in 6 (22%) and 4 (15%) tumours, respectively." (PMID 30641862, 2019). "ARID1B immunoreactivity was detected in tumor cell nuclei and high expression was observed in 45/53 (85%) samples whereas low expression was observed in 8/53 (15%) samples." (PMID 29890703, 2018). "The largest subunit in SWI/SNF, named AT-rich interactive domain containing protein 1B (ARID1B), has been recently characterized to play tumor suppressor activity." (PMID 28415691, 2017). "We found that ARID1B OE significantly promoted tumor growth." (PMID 40671262, 2025). "Notably, IPZ treatment effectively abolished the tumor‐promoting effects of ARID1B OE, resulting in tumor growth comparable to the control group." (PMID 40671262, 2025). "This study identifies ARID1B as a chromatin‐bound driver of tumor growth in TNBC." (PMID 40671262, 2025). "Furthermore, ARID1B expression positively correlated with the proliferative marker Ki67, indicating the link between ARID1B levels and tumor cell proliferation." (PMID 40671262, 2025). "Finally, we discovered that by suppressing ARID1B function via blocking its nuclear import or via KO of the ARID1B gene in vivo, we not only inhibited tumor growth but also augmented the therapeutic efficacy of PARP inhibitors in treating TNBC tumors." (PMID 40671262, 2025). "Additionally, ARID1B KO was shown to significantly suppress tumor growth, with an even more marked reduction in the ARID1B KO group treated with Niraparib." (PMID 40671262, 2025). "As MNAC is an HPV-independent neoplasm, it follows a distinct pathophysiology and has been linked to several genetic mutations, including KRAS/NRAS, ARID1A, ARID1B, SMARCA4, and CTNNB1 mutations, along with chromosomal alterations such as gains of 1q, chromosomes 10 and 12, and loss of 1p." (PMID 39797200, 2024). "Moreover, the tumor suppressors ARID1B, CDKN2A and NF1 were commonly affected by chromosomal copy loss." (PMID 38191367, 2024). "As the ARID1A and ARID1B proteins are mutually exclusive in the SWI/SNF complex, it could be proposed that the survival of tumor cells with ARID1A mutations may depend on the presence of ARID1B in the residual SWI/SNF complex." (PMID 37175555, 2023). "These same ARID1B-modulated gene networks may also contribute to various blood disorders as well as the uncontrolled growth seen in some tumor types in which cells must thrive in very oxygen-poor environments." (PMID 35672450, 2022). "The analysis revealed that ARID1B hypermethylation could serve as an early diagnostic biomarker for COAD treatment, and the difference in immune cell infiltration was found to be related to the ARID1B expression of the COAD tumour." (PMID 36313455, 2022). "In the context of HCC, Tordella et al89 identified that ARID1B serves as a regulator of oncogene‐induced senescence (OIS) and represents a potent tumour suppressor mechanism; they described that knock‐down of ARID1B prevented OIS and cooperated with RAS to induce liver tumours." (PMID 32162380, 2020). "This SMARCA4-WT tumour demonstrated somatic mutations in genes encoding two other subunits of the SWI/SNF remodelling complex: AT rich interactive domain 1 A (ARID1A) and AT rich interactive domain 1B (ARID1B)." (PMID 31844183, 2020).